HLA-C (major histocompatibility complex, class I, C)
Diseases named in the same sentence as HLA-C in open-access papers (continued):
Sharing a sentence is not in itself a finding about the gene and the disease.
psoriasis (continued). "In association studies, the lncRNA PSORS1C3, located in PSORS1 (in 6p21.3) and near to HLA-C gene region, was also related to psoriasis susceptibility." (PMID 29751665, 2018). "Meanwhile, there is a pseudogene XXbac-BPG299F13.15 which is located in the same LD region as HLA-C and is interacting with 4 other literature reported psoriasis-associated genes (PSORS1C1, MICA, HCP5, HLA-C)." (PMID 30315195, 2018). "Most of these novel potential psoriasis-associated SNPs are reported to be Expression quantitative trait loci (eQTLs) of known psoriasis-associated genes like HLA-B and HLA-C in GTEx Portal29." (PMID 30315195, 2018). "Due to low allele frequency in the Japanese population, the impact of HLA-C*06:02 on psoriasis susceptibility in Japanese psoriasis patients was less apparent compared with that seen in other populations (2.3% in psoriasis cases and 0.4% in controls)." (PMID 29760713, 2018). "The fact that in our population HLA-C*06:02 was strongly associated with psoriasis both in males and females supports the HLA-C-independent association of rs887466 with this disease." (PMID 29589160, 2018). "SNP rs27044 has been prioritized to be a causal variant for autoimmune diseases, and interacts with HLA-C*06 in the development of early onset psoriasis patients." (PMID 29715312, 2018). "Like other autoimmune conditions, the strongest genetic association with psoriasis is with a specific HLA allele HLA-C*06:02, with those presenting with early onset (or type 1 psoriasis) having a higher prevalence of HLA-C*06 expression." (PMID 30054427, 2018). "Aside from HLA-C*06:02 psoriasis associated with HLA-C*12:03, HLA-C*07:01, HLA-C*07:02, HLA-C*07:04, HLA-B*27, and HLA-B*57." (PMID 29760713, 2018). "The established HLA association in adult-onset PsA is HLA-C*0602,21 which is also the primary HLA association in psoriasis, was also modestly associated in this study (p=0.008)." (PMID 27998952, 2017). "HLA-C*06:02 (equivalent to HLA-Cw6) was most strongly associated with susceptibility to psoriasis (OR = 3.26; P = 2.1 × 10–201) and is also protective against HIV infection (OR = 2.97; P = 2.1 × 10 –19)." (PMID 28449694, 2017). "Of note, HLA-C*06:02 is known as the HLA locus with the strongest genetic association with psoriasis." (PMID 27158469, 2016). "We showed the combined genetic association of LCE3 and HLA-C risk alleles in Indian psoriasis patients." (PMID 27048876, 2016). "Nevertheless, HLA-C*06 is estimated to be responsible for less than 50% of genetic predisposition to psoriasis." (PMID 27658291, 2016). "Out of the five tested psoriasis susceptibility markers, only HLA-C*06 and rs26653 G alleles showed statistically significant association with the disease." (PMID 27658291, 2016). "Amongst 10 genes identified in the locus, HLA-C*06 is considered to be the main psoriasis susceptibility marker." (PMID 27658291, 2016). "While HLA-C*0602 is associated with an earlier diagnosis of psoriasis, it is associated with a later diagnosis of PsA29." (PMID 27928500, 2016). "The combination of nine non-MHC genetic markers presented similar association with the risk of psoriasis to HLA-C." (PMID 27658291, 2016). "The computed odds ratios revealed that within five genetic polymorphisms evaluated in this study, HLA-C*06 demonstrated the strongest effect on the risk of psoriasis." (PMID 27658291, 2016). "The early-onset psoriasis is considered more severe and is associated with HLA-C*06 when compared with late-onset psoriasis." (PMID 25685842, 2015). "Other authors found an association between rs10484554 (HLA-C) and type I psoriasis compared with type II psoriasis (OR = 3.24 in type I)." (PMID 26613086, 2015). "In conclusion, our study confirmed an association between rs12191877 (HLA-C) and type I psoriasis and between type I and type II psoriasis patients." (PMID 26613086, 2015).
psoriasis (continued). "Node 16 corresponds to rs7773175, which is upstream from HLA-C, a gene that has been associated with psoriasis over decades of research efforts." (PMID 25233071, 2014). "Our study confirmed the strong positive association of psoriasis with HLA-C*06, observed mainly in Caucasoid populations as well as in several other ethnically different groups." (PMID 23184486, 2013). "Two other recent GWAS identified ERAP1 as a new psoriasis susceptibility locus and evidence of an interaction between HLA-C*06:02 and ERAP1 was reported." (PMID 22942706, 2012). "We found that the association of rs67384697 with psoriasis was largely driven by HLA-C*06:02, since conditioning on HLA-C*06:02 resulted in only a marginally significant p-value for rs67384697 (p = 0.044, OR = 1.12)." (PMID 22577363, 2012). "Both studied revealed that ERAP1 influences psoriasis susceptibility only in individuals carrying the HLA-C risk allele." (PMID 22942706, 2012). "The previously reported MHC Class I region including HLA-C and HLA-B (associated with psoriasis and ankylosing spondylitis, respectively) was associated only in the EA dataset." (PMID 22952805, 2012). "We identified HLA-C*06:02, B*38:01, A*02:01, B*39:01, B*27:05, B*08:01, B*14:02, B*55:01, and B*57:01 as HLA class I alleles independently associated with psoriasis." (PMID 22577363, 2012). "This is expected because two SNPs are in strong LD (r2 = 0.935, D′ = 0.998) and both are good approximate to HLA-C*0602, known to be associated with psoriasis." (PMID 22125590, 2011). "Within PSORS1 is the human leukocyte antigen-C (HLA-C) gene which is the strongest candidate gene for psoriasis identified to date, with its allele HLA-Cw*0602 shown to be the predominant risk allele." (PMID 21295490, 2011). "SNP rs3130457 in POU5F1 tags the classical HLA-C*0602 allele, while rs10484554 in HLA-C is the most significant SNP associated with psoriasis and psoriatic arthritis in European ancestry population." (PMID 22125590, 2011). "SNP rs9468925 in HLA-C/HLA-B consistently appears in all four regression models, indicating that an independent HLA locus is associated with psoriasis." (PMID 22125590, 2011). "Minor allele at rs9468925 in HLA-C/HLA-B appear to be negatively associated with psoriasis in all four models (OR = 0.53–0.65, P = 1.22e-08 to 1.70e-05)." (PMID 22125590, 2011). "This question turns out to be challenging because any other putative psoriasis predisposing genes would have a weaker effect than HLA-Cw*0602, and the analyses would be complicated by potential linkage disequilibrium with HLA-C." (PMID 19680446, 2009). "Recently, sequencing and haplotype analyses studies have concluded that HLA-C is the major risk determinant of psoriasis within the HLA region, and HLA-Cw*0602 is the main risk allele." (PMID 19680446, 2009). "Recently, we carried out a genome-wide association scan (GWAS) on psoriasis with 1,359 patients and 1,400 healthy controls, which identified seven psoriasis loci in the human genome and confirmed the effect of HLA-C." (PMID 19680446, 2009). "Recently, a genome-wide scan reveals that a SNP rs12191877, which is 13 kb upstream of the HLA-C gene, shows strong association to psoriasis in European and is in linkage disequilibrium with the HLA-Cw6 haplotype." (PMID 19308260, 2009). "Individuals carrying risk genotypes at HLA-C, rs2073048 and rs13437088 were estimated to be at a nine-fold increased risk of psoriasis compared to those carrying low risk genotypes at all three loci." (PMID 19680446, 2009). "A marker D6S2931 is located in PSORS1 at 6q21.3 near the HLA-C gene, which has been shown to be significantly linked and associated with psoriasis." (PMID 19308260, 2009). "As expected, only the haplotypes carrying either HLA-Cw6 (HLA-C haplotype 11) or CDSN*TTC (CDSN haplotype 2) allele are positively associated with psoriasis." (PMID 18369457, 2008).
psoriasis (continued). "A 150-kb region telometic to HLA-C was also shown to be associated with psoriasis in a Jewish population." (PMID 18369457, 2008). "The established association of HLA-C*06 with susceptibility to psoriasis provides a clear precedent for the involvement of HLA-C in complex inflammatory disease." (PMID 17252545, 2007). "The autoantigenic peptides can also be presented by other HLA class I molecules associated with psoriasis, suggesting that they may have antigenicity in the pathogenesis of psoriasis beyond HLA-C*06:02." (PMID 41440022, 2025). "The data presented here provide new insights into the pathomechanisms that may transform the main phenotype-specific risk association of psoriasis with HLA-C*06:02 into an active autoimmune disease." (PMID 41440022, 2025). "The pronounced downregulation of HLA-C on melanocytes could render psoriasis, as HLA-C-associated disease, particularly susceptible to this effect." (PMID 40243413, 2025). "Due to the particularly pronounced effect on HLA-C expression, psoriasis, as an HLA-C-associated T-cell-mediated autoimmune disease, may be particularly susceptible to UVB phototherapy." (PMID 40243413, 2025). "Using a Vα3S1/Vβ13S1 T-cell receptor (TCR) from a lesional psoriatic CD8+ T-cell clone, we recently demonstrated that in psoriasis, the major psoriasis risk allele HLA-C*06:02 mediates an autoimmune response of CD8+ T-cells against melanocytes by presenting a melanocyte autoantigen." (PMID 40243413, 2025). "The almost 10% predisposition for psoriasis identified in our cohort through the presence of the HLA-C*06:02:01 allele would single out this HLA-C*06:02 variant for genetic testing in individuals with a diagnosis of a family history of or clinical indications for this disorder." (PMID 39201523, 2024). "Also associated with psoriasis pathogenesis: HLA-C*18, HLA-B57, HLA-DR*07, HLA-DQA1*:02:01 and DQB*:02:02." (PMID 38612637, 2024). "Within a complex genetic predisposition, HLA-C*06:02 is the main psoriasis-specific risk gene." (PMID 38524140, 2024). "HLA-C*12:02 has also been documented for its association with psoriasis." (PMID 38535155, 2024). "Exclusion of variants mapped to the HLA-C locus, an established risk locus for psoriasis resulted in highly similar associations compared to our primary model, indicating the contribution of the genetic variability mapped to non-GWS variants in PRS computations." (PMID 39568675, 2024). "Furthermore, their HLA-C*06:02-positive patients with a late age of onset were associated with mild psoriasis, while their HLA-C*06:02-negative patients with a late age of onset were associated with more severe psoriasis." (PMID 39261909, 2024). "In past GWAS studies of psoriasis, HLA-C has been identified as a highly associated locus." (PMID 37323656, 2023). "Three of the identified psoriasis risk variants had a stronger association with PsC than PsA (rs12189871 near HLA-C, rs4908742 near TNFRSF9, rs10888503 near LCE3A), whereas two had a stronger association with PsA than PsC (rs12044149 near IL23R, rs9321623 near TNFAIP3)." (PMID 36826011, 2023). "Our results show that the HLA-C*07 allele was significantly associated with late age of disease onset (p = 0.007), suggesting it could be a biomarker for late psoriasis onset, at least in Moroccan patients." (PMID 36826011, 2023). "HLA-C*0602 is associated with EOP both in patients with psoriasis and psoriatic arthritis (PsA)." (PMID 37834254, 2023). "Indeed, CD8+ T cells that react against melanocyte-derived antigens have been identified in psoriasis associated with HLA-C*0602." (PMID 37628670, 2023). "HLA-C gene polymorphisms have been related to ethnic differences; thus, other genetic and environmental factors may play a role in psoriasis susceptibility and severity." (PMID 36826011, 2023).
psoriasis (continued). "In particular, the HLA-C rs12191877 polymorphism was associated with the response to anti-TNF drugs (a reduction of 75% in psoriasis area and severity index score [PASI 75] at 3 months) in 144 white patients (from Spain) (OR = 0.30, 95% CI = 0.11–0.88, p = 0.027)." (PMID 37240048, 2023). "Future studies exploring the functional role of specific HLA-C alleles in IFN-γ/IL-17-dependent immune responses will be fundamental not only to unveil their pathogenic activity in psoriasis but also to understand why specific HLA-C haplotypes effectively respond to the ustekinumab treatment." (PMID 36423071, 2022). "Furthermore, patient SN3, who is affected by PsA, carries the allele HLA-C*06:02:01:01, which has been linked with the development of PsA/psoriasis." (PMID 36294757, 2022). "Also, this approach has shown that guttate psoriasis patients positive for the HLA-C predisposing allele and/or the ASO perform increased cutaneous pro-inflammatory response by CLA+ T cells." (PMID 34778294, 2021). "However, after adjustment for the top psoriasis allele HLA-C*06:02, these associations were altered in the dominant model, with only HLA-C2 and HLA-Bw4 remaining significant." (PMID 34177931, 2021). "More interestingly, peptide motifs of the HLA-C*07:01, -C*07:02, and -B*27, which are three of the other psoriasis risk-related leukocyte antigens, utilize the same anchor residues with the HLA-C*06:02, have overlapping peptide-binding properties, and belong to the same HLA supertype." (PMID 33581710, 2021). "Synovial/entheseal counterpart of this picture is yet to be studied but seems to be more complicated since different disease phenotypes in PsA exhibit different HLA associations and contribution of the HLA-C*06:02 polymorphism to PsA risk is lesser compared to psoriasis." (PMID 33581710, 2021). "Finally, we explored how the combination of rs35569429 and HLA-C*06:02 affects PASI75 response in cohort 1 and 2 at week 12, since HLA-C*06:02 is an allele previously established to be associated with a more favorable responses to ustekinumab in psoriasis." (PMID 35154085, 2021). "Expression of HLA-C in T cells showed strong causal association with autoimmunity, in particular positive causal effects on psoriasis, SLE, PSC, multiple sclerosis, IBD, and ulcerative colitis; and negative causal effects on juvenile idiopathic arthritis, PBC, and rheumatoid arthritis." (PMID 32724101, 2020). "Moreover, each copy of the HLA-C*06:02 allele carried causes a five-fold increase in the risk of psoriasis." (PMID 33419370, 2020). "HLA-C*06:02 status is associated with different presentations of psoriasis." (PMID 33419370, 2020). "Finally, we found that all the HS patients with paradoxical reactions carried allelic variants in genes predisposing to classical psoriasis, including SNPs in the HLA‐C genomic region." (PMID 31577850, 2020). "Our study is limited as we could not investigate other potentially related alleles other than HLA-C alleles and risk factors increasing severity of psoriasis." (PMID 31341424, 2019). "Similarly, no strong evidence of a causal effect was found when performing two-sample MR analysis with the variant at HLA-C*06:02 (rs13200483) alone, (0.03 kg/m2 change in BMI per doubling odds of psoriasis, 95% CI −0.02 to 0.07, P = 0.24)." (PMID 30703100, 2019). "HLA-C⁎06, HLA-C⁎12, and HLA-C⁎04 alleles were most commonly observed in psoriasis patients." (PMID 31341424, 2019). "The HLA-C locus on chromosome 6p21.33 is accepted as a susceptibility locus for psoriasis." (PMID 31341424, 2019). "Thus, understanding psoriasis pathogenesis has to explain the role of HLA-C*06:02 within the complex genetic background predisposing to psoriasis." (PMID 29760713, 2018).
psoriasis (continued). "The association with HLA-C*06:02 in psoriasis is particularly intriguing because only 3 of more than 12,000 different HLA-class I alleles show a strong disease linkage: HLA-B*27 with ankylosing spondylitis, HLA-B*51 with Behçet’s disease, and HLA-C*06:02 with psoriasis." (PMID 29760713, 2018). "Nonamer peptides that ligated the Vα3S1/Vβ13S1-TCR displayed arginine at residues 2 and 7, and leucine at residue 9 and thus corresponded to the conserved amino acid pattern which is preferentially presented by HLA-C*06:02 and other psoriasis-associated HLA-class I molecules." (PMID 29760713, 2018). "Given the strong risk effect of HLA-C*06:02, the ethnic allele frequency spectra of HLA-C*06:02 may at least partially explain the heterogeneity of psoriasis in different ethnic populations." (PMID 29760713, 2018). "The actual immunological role of HLA-class I molecules suggests that HLA-C*06:02 may predispose to psoriasis by presentation of an autoantigen from a skin-specific cell population." (PMID 29760713, 2018). "Sequence-based methods in large samples finally proved HLA-C*06:02 as the main psoriasis risk gene." (PMID 29760713, 2018). "This type of psoriasis displays both strong association with HLA-C*06:02 and strong family history." (PMID 29589160, 2018). "Interestingly, several of the psoriasis-associated HLA-class I alleles are also significantly increased in Crohn’s disease (HLA-C*06:02, HLA-C*12:02) and ulcerative colitis (HLA-C*12:02, HLA-C*07:02)." (PMID 29760713, 2018). "Therefore, this review will focus on the functional implications of the main HLA psoriasis risk gene, HLA-C*06:02." (PMID 29760713, 2018). "We found significant association of HLA-C*06:02 allele dose with a younger age of psoriasis onset in all samples (p=1.01×10−59) and that carriage of the risk allele resulted in a difference in the median age of psoriasis onset of approximately 14 years." (PMID 28821532, 2017). "Given the previously reported association of HLA-C*06:02 with age of psoriasis onset, we investigated the potential for confounding of the statistical analysis due to selection bias in a data set of 2050 case-only samples with relevant phenotype data (PsA=981, PsC=1069)." (PMID 28821532, 2017). "For example, linkage disequilibrium mapping revealed that the PSORS1 is located in the proximity of HLA-C, which could cause the narrowing of the critical interval for the psoriasis susceptibility gene." (PMID 29232931, 2017). "Similar observations were reported from the Dublin cohort, where it was also reported that the presence of HLA-B*27 was associated with the early development of PsA among patients with psoriasis but the presence of HLA-C*06 was associated with a delayed onset of PsA29." (PMID 27928500, 2016). "Our aim was to compare psoriasis genetic risk score (GRS) for five susceptibility loci involved in the immunological response (HLA-C, ERAP1, ZAP70) and in the skin barrier function (LCE3, CSTA) between patients with chronic plaque psoriasis (n = 148) and the control group (n = 146)." (PMID 27658291, 2016). "HLA-C*0602 is the allele most strongly associated with psoriasis and is also a risk factor for PsA." (PMID 27928500, 2016). "Anyway, our results show the developed panel of five susceptibility loci to be more efficient in predicting psoriasis risk and to possess higher sensitivity and specificity for the disease than any of the markers analyzed separately, including the most informative HLA-C*06 allele." (PMID 27658291, 2016). "The results of our study confirm that the combination of HLA-C*06, rs26653 G, LCE3C_LCE3B-del, rs17589 T and rs17695937 G displays a very significant effect on the risk of psoriasis and may be used in practice for its prediction." (PMID 27658291, 2016). "Interestingly, an association with HLA-C*06 is also seen in psoriasis, replication of this finding is however necessary." (PMID 25521205, 2014).